GAPDH (glyceraldehyde-3-phosphate dehydrogenase)
Diseases named in the same sentence as GAPDH in open-access papers (continued):
Sharing a sentence is not in itself a finding about the gene and the disease.
prediabetes (2 papers, 2019 to 2022). "In LOsG-induced prediabetes, although pancreatic ROS stress remained high on LOsG treatment day 38, there were no alterations in mRNA levels of ER stress (XBP1 and BIP), inflammation (IL6 and IL1β), and hypoxia-responsive (HIF1α and GAPDH) genes between LOsG- and sham-treated groups." (PMID 30975975, 2019).
prostate adenocarcinoma (2 papers, 2010 to 2022). "Several studies reported an increase of GAPDH expression in cancer cell lines and shows that it has roles in the neoplastic transformation of hepatocytes, tumor cell motility and metastasis in rat prostate adenocarcinoma tissue, and in the detoxification of cisplatin and doxorubicin in cancer cells." (PMID 21073742, 2010).
pulmonary TB (2 papers, 2020 to 2025). "In clinical research—including studies of pulmonary TB—the genes GAPDH, ACTB, B2M or ribosomal RNA genes are most frequently chosen as reference genes." (PMID 41303702, 2025). "Normalization with a RG which shows varying expression across samples can often lead to wrong conclusions as seen with the use of Glyceraldehyde-3-Phosphate Dehydrogenase (GAPDH) as RG in gene expression studies of pulmonary tuberculosis and CD8+ T-cells under inactivated or activated condition." (PMID 32785215, 2020). "To identify the most stable HKGs for analyzing material from patients with pulmonary TB, we selected eight genes—ACTB, B2M, GAPDH, HPRT1, PPIA, RPL13A, YWHAZ and UBC—that are most commonly employed as reference genes in clinical studies." (PMID 41303702, 2025).
Rectal Tumors (2 papers, 2020 to 2023). "In the validation phase, 10 new rectal tumors were evaluated taking the geometric mean of GAPDH and PUM1 as the reference gene." (PMID 33457124, 2020). "However, in rectal tumors, we found GAPDH, PUM1, and RPN1 with the most stably expressed reference genes." (PMID 33457124, 2020). "Using GAPDH and PUM1 as the reference gene for the validation phase, rectal cancer patients with stage III/IV showed a 4.79-fold change (P=0.006) in ALDH1 expression, and an 11.76-fold change in Twist expression (P=0.003) with respect to stage II rectal tumor when normalized with GAPDH and PUM1." (PMID 33457124, 2020). "Gene expression was evaluated by qPCR using GAPDH as a reference, which has been previously validated as one of optimal, most stably expressed housekeeping genes for gene expression-related experiments in rectal tumors, which was confirmed in our cohort as well." (PMID 37719698, 2023). "GAPDH and PUM1 can be used as an optimal set of housekeeping genes for gene expression-related experiments in rectal tumors." (PMID 33457124, 2020). "The GAPDH and PUM1 combination was used successfully for normalization in the experiment related to the CSCs and EMT markers ALDH1, E cadherin, vimentin, and Twist expression in rectal tumors." (PMID 33457124, 2020). "GAPDH, RPN1, and PUM1 could be used as a suitable reference gene for gene expression-based qPCR experiments in rectal tumors." (PMID 33457124, 2020). "Five promising reference genes GAPDH, Pumilio RNA binding family member 1 (PUM1), beta-2-microglobulin (B2M), ribophorin I (RPN1), and phosphomannomutase 1 (PMM1) were selected from different publications to assess their expression stability in rectal tumors as part of the screening phase." (PMID 33457124, 2020).
retinoblastoma (2 papers, 2023). A malignant tumor that originates in the nuclear layer of the retina. "Because the ddPCR technique was more sensitive for GAPDH in retinoblastoma samples, we selected GAPDH as the nucleus‐encoded sequence to calculate the mitochondrial‐to‐nuclear DNA ratios in AH samples." (PMID 36148636, 2023). "Among retinoblastoma patients in the Progression‐free group, the area under the ROC curve (AUC) for GAPDH copies in AH was 0.86 (95% CI, 0.71–1.00), compared with the Progressive RB group." (PMID 36148636, 2023). "The sequences of B4GALNT1 and GAPDH, both in chromosome 12, are highly conserved in retinoblastomas, and in genomic regions away from areas that include frequent alterations such as RB1 (chromosome 13q) and MYCN (chromosome 2p)." (PMID 36148636, 2023). "The optimal cut‐off point for discriminating between progressive and progression‐free retinoblastomas was 108 GAPDH copies per reaction." (PMID 36148636, 2023). "Quantification of nuclear GAPDH copies in AH may complement fundoscopy to detect active intraocular retinoblastoma." (PMID 36148636, 2023). "OpenTarget Tool software indicated that glyceraldehyde 3-phosphate dehydrogenase (GAPDH) and CD44 were also more highly expressed in the retinoblastoma." (PMID 37658463, 2023).
rheumatoid arthritis (2 papers, 2019 to 2023). A chronic, systemic autoimmune disorder characterized by inflammation in the synovial membranes and articular surfaces. "The potent inflammatory and MMPs inhibitory efficacy of SHP-47B was also observed in an animal model of rheumatoid arthritis induced by MIA (monosodium iodoacetate), which is known to induce rheumatoid arthritis as a glyceraldehyde-3-phosphate dehydrogenase inhibitor." (PMID 37623223, 2023).
Salmonella Infections (2 papers, 2021). Infections with bacteria of the genus SALMONELLA. "Salmonella infection induced VDR mRNA expression (normalized to GAPDH) in Caco-2 cells after one-hour infection, which was synergically enhanced using a combination of butyrate and 1,25D3." (PMID 34680413, 2021). "Salmonella infection induced VDR mRNA expression (normalized to GAPDH) in SW480 cells, which was synergistically enhanced by combination of Bifidobacterium longum and 1,25D3." (PMID 34576700, 2021).
schistosomiasis (2 papers, 2015 to 2021). An infectious disease caused by parasitic trematodes of the genus Schistosoma that colonize human blood vessels and release eggs that can cause granulomatous reactions leading to acute (swimmer's itch or acute schistosomiasis syndrome) or chronic disease. "Investigation of antibody responses to schistosomiasis identified glyceraldehyde-3-phosphate dehydrogenase (GAPDH) as a major antigen inducing a short-lived antibody response." (PMID 25706299, 2015).
steatosis (2 papers, 2018 to 2019). Increased lipid within the cytoplasm of cells. "GHR expression levels were comparable in patients with simple steatosis and NASH (GHR/GAPDH cDNA ratio: 3.94 ± 1.82 in simple steatosis vs 3.53 ± 1.42 in NASH)." (PMID 30206761, 2018). "This is the first report to identify the interaction of full-length DENV2 NS3 and its domains with the GAPDH protein and to demonstrate that this interaction may play an important role in the molecular mechanism that triggers DENV-promoted steatosis." (PMID 30804377, 2019). "G6Pase/GAPDH cDNA levels tended to be higher in patients with NASH than in patients with simple steatosis without reaching statistical significance (1.42 ± 0.96 vs. 0.97 ± 0.58, p = 0.18)." (PMID 30206761, 2018).
streptococcal infection (2 papers, 2017 to 2026). Any of the several infectious disorders caused by members of streptococcus, a genus of gram positive bacteria belonging to the family Streptococcaceae. "In addition to its well-established role in carbohydrate metabolism, D-glyceraldehyde-3-phosphate dehydrogenase (GAPDH) from Streptococcus pyogenes and S. pneumoniae have been reported to act as extracellular virulence factors during streptococcal infections." (PMID 28443070, 2017). "The involvement of the extracellular GAPDH of S. pyogenes in C5a sequestration and of the S. pneumoniae enzyme in C1q binding provide reference cases for the existence of complement immunoevasion mechanisms in streptococcal infections that depend on the moonlighting action of GAPDH." (PMID 28443070, 2017).
varicocele (2 papers, 2017 to 2020). A condition characterized by the dilated tortuous veins of the spermatic cord with a marked left-sided predominance. "Expression levelof GAPDH was not different in non-varicocele andvaricocele-induced testes." (PMID 28868836, 2017). "For example, glyceraldehyde 3 phosphate dehydrogenase (GAPDH) and malate dehydrogenase (MDH) have not been detected in patients with varicocele." (PMID 33266209, 2020).
Warthin tumor (2 papers, 2020 to 2024). An adenoma characterized by an oncocytic, often papillary, epithelial component, dense lymphoid stroma, and cystic spaces. "The observed progressive GAPDH loss in Warthin tumor oncocytes could be implicated in the pathogenesis of Warthin tumors." (PMID 32365590, 2020). "Based on these initial observations, the present study aimed to evaluate the potential role of GAPDH in the pathogenesis of Warthin tumors." (PMID 32365590, 2020). "Remarkably, a preliminary Western blot analysis using crude lysates of presumed Warthin tumors and normal parotid gland tissues exhibited strikingly different GAPDH expression levels that could not be explained by differences in protein loading only." (PMID 32365590, 2020).
Zinc deficiency (2 papers, 2018 to 2025). A deficiency of the essential metal Zinc; an essential cofactor for many enzymes. "At a protein level, zinc deficiency not only reduced Mb expression but also decreased GAPDH levels, suggesting impaired overall cell metabolism." (PMID 41347147, 2025). "In addition to zinc deficiency, a high level of Zn2+ can inhibit glycolysis via its inhibitory effects on glyceraldehyde-3-phosphate dehydrogenase (GAPDH), phosphofructokinase, and muscle pyruvate kinase; however, these effects can be reversed by a high level of histidine." (PMID 29743987, 2018).
abortion (1 paper, 2025). the ending of pregnancy by removing a fetus or embryo before it can survive outside the uterus. "Week of pregnancy, GAPDH, and IL-27 were significantly lower in spontaneous abortion patients than healthy pregnant women (p < 0.05)." (PMID 40141672, 2025).
Acidosis (1 paper, 2025). Abnormal acid accumulation or depletion of base. "Acidosis inhibits the activity of BPGM, thereby reducing levels of 2,3-BPG, while the increased lactate/NADH ratio suppresses glyceraldehyde-3-phosphate dehydrogenase (GAPDH) activity, leading to reduced formation of 1,3-BPG and consequently decreased 2,3-BPG production." (PMID 41199853, 2025).
acne (1 paper, 2024). An inflammatory process of the sebaceous glands which is characterized by comedones, nodules, papules and/or pustules on the skin. "Based on the PPI network analysis and topology algorithm in Cytoscape software, TNF, GAPDH, IL6, Albumin (ALB), and protein kinase 1 (AKT1) are considered to be the core target proteins for the treatment of acne." (PMID 39029003, 2024).
Acute hepatitis (1 paper, 2018). Acute hepatic injury resulting from inflammation typically accompanied by increased serum alanine transaminase activity. "Serum miRNA-122 analysis, normalized for glyceraldehyde-3-phosphate dehydrogenase expression revealed a significant increase in acute hepatitis accompanied with elevation in ALT and AST, while in chronic hepatitis, elevation of serum miRNA-122 was accompanied with ALT and AST of the normal range." (PMID 29915506, 2018).
acute leukemia (1 paper, 2024). A clonal (malignant) hematopoietic disorder with an acute onset, affecting the bone marrow and the peripheral blood. "In order to identify the best reference genes for gene expression studies in peripheral blood and/or bone marrow samples of acute leukemia patients, a qPCR assay based on TaqMan detection for the expression analysis of the six selected genes (ACTB, ABL, GAPDH, HPRT, TBP and RPLP0) was used." (PMID 38397141, 2024). "From these results, it can be considered that GAPDH and HPRT do not behave as good endogenous genes for the expression analysis of acute leukemia samples; therefore, they should not be used." (PMID 38397141, 2024).
acute pancreatitis (1 paper, 2016). An acute inflammatory process that leads to necrosis of the pancreatic parenchyma. "Similar to GAPDH, 18sRNA may represent a suitable reference gene in mouse caerulein-induced acute pancreatitis, or the early phase (within 3 h after LPS injection) of mouse acute pancreatitis by caerulein and LPS." (PMID 27069927, 2016). "In studies of caerulein-induced murine acute pancreatitis, ACTB, GAPDH, 18sRNA, beta-2 microglobulin (B2M), and hypoxanthine phosphoribosyltransferase 1 (HPRT1) have been frequently used as reference genes for comparison of mRNA transcription in pancreatic tissue." (PMID 27069927, 2016).
albinism (1 paper, 2017). A congenital disorder characterized by partial or complete absence of melanin pigment in the eyes, hair, or skin. "The opposite trend was observed for GAPDH (CSA016761.1; 5- and 3-fold lower, respectively), suggesting that the two proteins are differentially regulated in ‘Anji Baicha’ during periodic albinism." (PMID 29312376, 2017).
alcoholic liver diseases (1 paper, 2014). A disorder caused by damage to the liver parenchyma due to alcohol consumption. "We chose 18S rRNA for our endogenous control, as it displays the least amount of variance in all stages of alcoholic liver disease in humans (compared to GAPDH, ACTB, and SFRS4)." (PMID 25542004, 2014).
allergic rhinitis (1 paper, 2012). Inflammation of the nasal mucous membranes caused by an IgE-mediated response to external allergens. "The ratio of H1 receptor/GAPDH in nasal mucosa from patients with nasal allergy was significantly higher than the ratio found in nasal mucosa obtained from nonallergic rhinitis (allergic rhinitis: 0.76 ± 0.24, nonallergic rhinitis: 0.39 ± 0.11, P = 0.03)." (PMID 23132961, 2012).
amelanotic melanoma (1 paper, 2024). A melanoma characterized by the complete absence of melanin pigment in the melanoma cells. "In three tumors that histomorphologically were compatible with STS or amelanotic melanoma, cat GAPDH was not detectable, and PCR results could not be interpreted." (PMID 38612342, 2024).
angioimmunoblastic T-cell lymphoma (1 paper, 2022). A mature T-cell non-Hodgkin lymphoma, characterized by systemic disease and a polymorphous infiltrate involving lymph nodes and extranodal sites. "The overexpression of GAPDH in the T cell lineage promotes angioimmunoblastic T cell lymphoma through an NF-κB-dependent mechanism." (PMID 37170359, 2022).
Aortic dissection (1 paper, 2025). Aortic dissection refers to a tear in the intimal layer of the aorta causing a separation between the intima and the medial layers of the aorta. "In addition to PGK1 and HMGA1, several other lactylation-related genes identified in our analysis, such as GAPDH and ALDH1A1, may also contribute to the pathophysiological mechanisms of aortic dissection." (PMID 40596702, 2025).
Apnea (1 paper, 2020). Lack of breathing with no movement of the respiratory muscles and no exchange of air in the lungs. "The redox–oligomeric states of GAPDH and PRDX2 involving overoxidation by sulfinic/sulfonic acids were differentially modulated in OSA RBC probably due to the nocturnal apnea-induced intermittent hypoxia that was chronically experienced by these patients." (PMID 33256145, 2020).
Arthritis (1 paper, 2023). Inflammation of a joint. "In a past study, HPRT1, B2M, and RPL13A were the stable genes in the arthritic joints of the KbxN serum transfer arthritis model, and the mRNA expression level of GAPDH significantly decreased with an increase in joint inflammation." (PMID 37894839, 2023).
astrocytic tumor (1 paper, 2007). A glial tumor of the brain or spinal cord showing astrocytic differentiation. "Based on these findings from other studies, our present results suggest that there is also no hypoxia-dependent regulation of GAPDH in astrocytic tumors in vivo." (PMID 17597534, 2007). "Therapeutic strategies for treatment of human astrocytic tumors involving GAPDH as target molecule do not represent a valid approach in conjunction with tumor hypoxia in the human brain." (PMID 17597534, 2007).
autoimmune hypothyroidism (1 paper, 2016). "Comparison of the findings showed significantly decreased expression of both full length and soluble CTLA4 in autoimmune hypothyroidism patients than in controls after normalization with GAPDH expression (p< 0.0001 and p = 0.01 respectively)." (PMID 26963610, 2016).
Azoospermia (1 paper, 2021). Absence of any measurable level of sperm,whereby spermatozoa cannot be observed even after centrifugation of the semen pellet. "The BOll/GAPDH mRNA ratio was assessed in different pathological phenotypes of azoospermia, and using a cut-off value of 0.5, sensitivity and specificity of 100% was achieved for SR13." (PMID 34158577, 2021).
bacterial meningitis (1 paper, 2013). Inflammation of the membranes surrounding the brain and spinal cord due to a bacterial infection. "We selected IL-1 beta, IL-6 and TNF alpha for the quantitative reverse transcriptase PCR, since they are known to be the major inflammatory cytokines detected in the CSF during bacterial meningitis, as control the house keeping genes GAPDH and HPRT1 were used." (PMID 23874613, 2013).
benign muscle tumor (1 paper, 2012). "The integrin αν of uterine leiomyoma (benign muscle tumor) was normalized to GAPDH and healthy tissues." (PMID 22889191, 2012).
bone metastasis (1 paper, 2016). Transfer of a neoplasm from its primary site to bones. "Finally, multivariate analysis including the panel of five CTC-biomarkers in combination with the presence of bone metastasis resulted in GAPDH, NOTCH1 and PTP4A3 as independent predictors of PFS; GAPDH and ITGB3 showed predictive value for OS." (PMID 27901069, 2016).
brain injury (1 paper, 2021). Acute and chronic (see also brain INJURIES, CHRONIC) injuries to the brain, including the cerebral hemispheres, CEREBELLUM, and brain STEM. "For example, RNS accumulation after a traumatic brain injury (TBI) is speculated to induce the S-nitrosylation of glyceraldehyde 3-phosphate dehydrogenase (GAPDH)." (PMID 34440890, 2021).
brucellosis (1 paper, 2024). Brucellosis is a bacterial infection that spreads from animals to people via unpasteurized dairy products or by exposure to contaminated animal products or infected animals. "In line with this, the enrichment of genes linked to the ‘interferon‐gamma response’ pathway (e.g., STAT1, IFNG, IRF1, B2M, GAPDH) was also consistently observed in brucellosis patients." (PMID 39135683, 2024).
Candidemia (1 paper, 2016). A form of invasive candidiasis where species of CANDIDA are present in the blood. "In this article, we show nearly complete sequence information for five discrete antigenic species of Candida albicans Tdh3 (glyceraldehyde-3-phosphate dehydrogenase), which have been reported to be differentially recognized both among candidemia patients and between candidemia and control patients." (PMID 26862568, 2016).
candidiasis (1 paper, 2024). Infection with the organism Candida. "In the current work, we comparatively analyzed the moonlighting protein status of GAPDH in C. albicans and Nakaseomyces glabratus (formerly C. glabrata)—two species that both cause human candidiasis but differ to some extent regarding pathogenic mechanisms." (PMID 38256088, 2024).
cervical adenocarcinoma (1 paper, 2020). An adenocarcinoma arising from the cervical epithelium. "To determine whether a chromatin donor template affects the efficiency of HDR in a different cell line, we examined the insertion of GFP sequences at the GAPDH locus in HeLa cells, which are human cervical adenocarcinoma cells that are widely used in biomedical research." (PMID 32343230, 2020).
chronic hepatitis C (1 paper, 2022). "To verify the results of the trial study, we examined the levels of the 9 proteins, IGHV, GAPDH, C1s, GRP78, V-ATPase, PPBP, CD9, Lp(a) and SAP, in EVs isolated from the sera of another 80 patients with chronic hepatitis C before DAA treatment." (PMID 35797333, 2022).